MIR3179-4 (microRNA 3179-4)
Synonyms: hsa-mir-3179-4
Gene: MicroRNA gene on chromosome 16 (18,494,493 to 18,494,576, reverse strand). Ensembl gene ENSG00000277014.
Gene Ontology:
Biological process: miRNA-mediated post-transcriptional gene silencing
Cellular component: RISC complex
Homologues: Paralogues in human: MIR3179-1 (100% identical), MIR3179-2 (100% identical), MIR3179-3 (100% identical).